MDM2 (MDM2 proto-oncogene)
Diseases named in the same sentence as MDM2 in open-access papers (continued):
Sharing a sentence is not in itself a finding about the gene and the disease.
cancer (continued). "The oncogene, mouse double minute 2 (MDM2), has been implicated in the pathogenesis of numerous cancers, where it stimulates the expression of matrix metalloproteinase 9 (MMP9), an important enzyme in the breakdown of the extracellular matrix." (PMID 24236052, 2013). "The diversity of mdm2 spliced messages encoded from two independent promoters has the capacity to increase the human cancer proteome." (PMID 24147044, 2013). "The MDM2 T309G polymorphism has been associated to several cancers and also to inflammatory processes." (PMID 24349246, 2013). "Meta-analysis studies have revealed that the presence of SNP 309T>G in the MDM2 gene is associated with the risk of cancer." (PMID 23565197, 2013). "Abnormal activation of Murine Double Minute 2 (MDM2) has been established as an important causative factor in human cancer development." (PMID 23638184, 2013). "By using the Duplex SmartAmp method, the association of the SNP 309T>G in the MDM2 gene with cancer risk will be studied in the future, and the corresponding results will be reported elsewhere." (PMID 23565197, 2013). "Taken together, the data from the studies on SNP309 and SNP285 strongly indicate fine tuning of MDM2 P2 promoter activity to be of importance for cancer risk." (PMID 22558411, 2012). "The importance of MDM2 expression in preventing cancer development is further underlined by the finding that the MDM2 promoter P2 SNPs 285 and 309 both modulate transcription factor binding and affect the risk of multiple cancer forms." (PMID 22558411, 2012). "It has been suggested that high MDM2 levels are associated with poor prognosis of several human cancers." (PMID 22911819, 2012). "Although, another complicating component is in cancer cells Mdm2 has many splice variants and the contribution of these variants to DNA repair is not known." (PMID 23208375, 2012). "Previous meta-analyses have been conducted on the association of MDM2 T309G polymorphisms with several other cancer risks." (PMID 22844496, 2012). "Previously, we reported in Myc oncogene-driven cancer, loss of one allele of Arf rescued the delay in tumorigenesis caused by Mdm2 heterozygosity, demonstrating Arf levels regulate Mdm2 during oncogene-induced tumorigenesis." (PMID 23029416, 2012). "Here, we present the first report assessing the impact of SNP344 status on MDM2 expression as well as cancer risk in large populations." (PMID 22558411, 2012).
cancer (continued). "The relevance of these findings was further substantiated by the discovery of Mdm2 mutations in the region that binds to L11 in human cancers." (PMID 21406728, 2011). "In people, there is a single nucleotide polymorphism in the Mdm2 gene that influences both Mdm2 gene expression and susceptibility to breast and other cancers." (PMID 21437245, 2011). "It was demonstrated that these cancer-associated mutations are confined to the central zinc finger of Mdm2 and specifically disrupt the interaction between Mdm2 and L11 or L5 in vitro." (PMID 21406728, 2011). "A cancer predisposition single nucleotide polymorphism at position 309 in the mdm2 gene P2 promoter (T→G) increases binding affinity for the SP1 transcription factor, leading to Mdm2 over-expression." (PMID 21223569, 2011). "A meta-analysis of 21 studies showed that ORs of a variety of cancers associated with the MDM2 GG and TG genotype were 1.17 (95% CI = 1.04-1.33) and 1.15 (95% CI = 1.03-1.28), respectively." (PMID 20398418, 2010). "Comparing the age at diagnosis among those affected with cancer, a significant average difference of 9.0 years was observed for the carriers of a G allele for the MDM2 SNP309 polymorphism compared to TT carriers (18.6 versus 27.6 years, P = 0.0087)." (PMID 20520810, 2010). "They noted a significantly earlier cancer onset in women with both a strongly positive estrogen receptor expression pattern and the G/G polymorphism at the MDM2 309 position." (PMID 19226467, 2009). "The effect of the MDM2 SNP 309 G/G on cancer risk has been recently reviewed in a meta- analysis by Wilkeming and colleagues." (PMID 19226467, 2009). "Other corroborating evidence comes from the observation that over-expression of MDM2 in cancer has been linked with increased levels of metastasis, poorer response to therapy and bad prognosis." (PMID 18828900, 2008).
cancer (continued). "Several studies have analysed the impact of the Mdm2 SNP309 on cancer risk in sporadic and hereditary malignancies and a recently published meta-analysis revealed that there is only little effect on the risk of common cancers from this SNP alone." (PMID 18577987, 2008). "Several narrative reviews acknowledge the potential of molecular-radiomics integration in BSTTs, referencing candidate markers such as IDH mutations, MDM2 amplification, and miRNA expression; but these are typically discussed hypothetically or in reference to parallel findings in other cancers." (PMID 40900793, 2025). "However, the effectiveness of MDM2 inhibition can vary depending on the specific cancer type and the underlying molecular mechanisms involved." (PMID 39802403, 2025). "Recent studies have highlighted that MDM2 genotypes may influence serum MDM2 levels, potentially contributing to cancer susceptibility." (PMID 39857959, 2025). "Since dual IRES-DENV2 could introduce Mdm2 expression in cells, there is a risk of transforming the cells into cancer cells." (PMID 39911252, 2025). "Thus, the MDM2 SNP309 (rs2279744) G-allele results in an elongated binding site for the transcription factor Sp1, leading to increased MDM2 expression, and several studies have linked the G-allele to an increased risk of various cancer forms." (PMID 39979836, 2025). "The MDM2 role in driving cancer drug resistance could underly the minimal DDLPS chemotherapeutic responses." (PMID 40961077, 2025). "However, this contrasts with other reports indicating that MDM2 overexpression is associated with poor prognosis in certain cancers." (PMID 40371345, 2025). "Furthermore, reduced expression of RPL22 was associated with increased proliferation of cancer cells, and resistance to Nutlin-3a, an MDM2 inhibitor." (PMID 40427096, 2025). "The promoter region of MDM2 harbors several single nucleotide polymorphisms (SNPs), including rs937282, rs939283, and rs2279744, which have been implicated in modulating MDM2 expression and influencing cancer risk." (PMID 39857959, 2025). "Additionally, there are several aME genes whose dysregulation is associated with cancers when misregulated, such as Mmp14, Nid1, Mdm2, Cd36, and Id3." (PMID 41223055, 2025). "The overexpression of MDM2 in human cancers has been associated with a poor prognosis." (PMID 39048965, 2024). "Consequently, inhibition of TOP2β degradation by an MDM2 inhibitor causes cancer cells to be more susceptible to VP-16 by promoting cancer cell apoptosis." (PMID 38263255, 2024). "The in silico studies suggested δ-curcumene, Ar-curcumene, Ar-turmerol, and Ar-turmerone as the most promising compounds in the oils based on their high binding energy scores with the NOX2, NF-κβ, and mdm2 proteins implicated in ROS, inflammation, and cancer, respectively." (PMID 39124928, 2024).
cancer (continued). "Concomitant amplification of KIT and MDM2/4 may be associated with resistance to anti-cancer immune therapy; thus, the importance of adequately providing the MDM2 assays." (PMID 38732333, 2024). "Although MDM2 amplification has been extensively studied because of its importance in promoting cancer, the molecular mechanisms underlying increased MDM2 expression in most tumors remain unclear." (PMID 39199272, 2024). "Importantly, targeting overexpressed MDM2 in cancer cell membranes causes the breakdown of cell membrane integrity, resulting in necrosis of cancer cell membranes." (PMID 37081989, 2023). "If there was a clinical trial indication at level C or D for a specific cancer type, such as amplification of MDM2 or FGFR1 or mutations of AKT1, ATM, CDK12, and PTEN, patients were considered as candidates for receiving treatment, although in most cases, no clinical trials were available." (PMID 36251535, 2023). "The MDM2 gene is expressed as different isoforms, and the full-length transcript of MDM2 encodes a protein of 491 amino acids that plays a critical role, where in many human cancers, the MDM2 oncogene is amplified or overexpressed, and high levels of MDM2 are associated with poor prognosis." (PMID 37297833, 2023). "MDM2 is upregulated in a multitude of cancers and is associated with a poor prognosis." (PMID 37509518, 2023). "On top of that, 13 cancer studies were used to assess the mutations and CNAs in the MDM2 protein sequence to determine whether the gene has functional relevance in LGG development." (PMID 37049742, 2023). "MDM2 is overexpressed in most cancers, and associated with chemotherapy resistance." (PMID 37291112, 2023). "Genomic amplification and altered MDM2 levels are associated with unfavorable prognosis, poor response to chemotherapy and target therapy, and adverse clinicopathological parameters in many cancers." (PMID 37314603, 2023). "Prominent exceptions are ligases frequently mutated in cancer such as MDM2, FBXW7, VHL, KEAP1 and BRCA1, as well as E3 ligases found in genome-wide association studies and phenotypic screens (for instance Parkin, ITCH) as well as serendipitous discoveries such as CRBN as a target of thalidomide." (PMID 36500212, 2022).
cancer (continued). "Similarly, the variant rs3730485 (also known as del1518) in MDM2 gene has been investigated in different populations, particularly in connection with cancer development." (PMID 35678683, 2022). "Therefore, the nuclear localization of AKT, EGFR, and MDM2, and the exclusion of nuclear FOXO3a, have been linked with enhanced drug resistance, poor prognosis, and unfavorable overall survival in various cancers." (PMID 34445495, 2021). "The negative regulation of MDM2 by ribosomal proteins contributes to the hypothesis that decreased ribosomal biogenesis (and thus decreased MDM2 inhibition) contributes to an increased cancer risk." (PMID 34065345, 2021). "Elevated levels of MDM2 protein strongly correlate with an increased risk of cancer." (PMID 34572735, 2021). "Ma Y., Bian J., Cao H. MDM2 SNP309 rs2279744 polymorphism andgastric cancer risk: a meta-analysis." (PMID 33959694, 2020).